MIR1255B2 (microRNA 1255b-2)
Synonyms: hsa-mir-1255b-2; MIR1255B-2; MIRN1255B2
Gene: MicroRNA gene on chromosome 1 (167,998,660 to 167,998,726, forward strand). Ensembl gene ENSG00000221545.
Homologues: Orthologues: chimpanzee ptr-mir-1255b (100% identical), macaque mml-mir-1255b (84% identical). Paralogues in human: MIR1255A (72% identical).